CLDN2 (claudin 2)
Diseases named in the same sentence as CLDN2 in open-access papers (continued):
Sharing a sentence is not in itself a finding about the gene and the disease.
inflammatory bowel disease (continued). "One of the interesting targets of miR-182-5p in the relation to IBD, is Claudin-2, which is one of the tight junction proteins downregulated in inflammatory bowel disease." (PMID 38408066, 2024). "In normal gut, claudin-2 was detected in the intestinal crypts and is overexpressed in inflammatory bowel disease (IBD), CRC, and other tumor types." (PMID 29134439, 2018). "Considering significant increases in claudin-2 expression in inflammatory bowel disease (IBD) and colon tumorigenesis, these findings can be harnessed for therapeutic advantage." (PMID 29152115, 2017). "In contrast, claudin-2, a TJP required for the formation of paracellular water channels that are highly expressed in leaky epithelial tissues, is up-regulated in inflammatory bowel diseases and promotes inflammation." (PMID 39459037, 2024). "Reduced expression of claudin-1 was observed in patients with inflammatory bowel disease (IBD) and irritable bowel syndrome (IBS), while an increase in claudin-2 was found in the inflamed epithelium of patients with ulcerative colitis (UC)." (PMID 37745643, 2023). "In inflammatory bowel disease, LPS or cytokines (e.g. IL-6 and IFN-γ) can activate JAK/STAT signaling pathway to regulate the expression of pro-inflammatory mediators including Claudin-2 and iNOS." (PMID 35436978, 2022). "Interestingly, claudin-2, which is abundantly expressed in leaky epithelia, is upregulated in inflammatory situations such as inflammatory bowel disease (IBD), deteriorating inflammation." (PMID 36364961, 2022). "Moreover, the effects observed in inflamed pleura, namely an induction of the paracellular pore claudin-2 and the decrease of tightening tight junction proteins are in accordance with regulatory mechanisms observed in inflamed epithelia, as shown e.g., for inflammatory bowel diseases." (PMID 25009499, 2014). "The intestinal proinflammatory immune factor and NF-κB could induce the decrease in claudin-1 expression inflammatory bowel disease, and BBR might regulate claudin-4 and claudin-2 expressions other than claudin-1 in claudin family." (PMID 28217099, 2017). "Moreover, recent evidence demonstrates that claudin-2 is involved in many signaling pathways, including vitamin D receptor, EGFR, and JNK signaling pathways, and it contributes to inflammatory bowel disease and colon cancer." (PMID 23505542, 2013). "In particular, TNF-α plays a critical role in inflammatory bowel disease, where it can synergize with IFN-γ to regulate multiple tight-junction (TJ) proteins, including myosin light chain kinase, occludin, and ZO-1, as well as claudin-1 and claudin-2 (106, –, 109), which are also regulated by IL-17." (PMID 32958528, 2020).
colorectal cancer (34 papers, 2009 to 2026). A primary or metastatic malignant neoplasm that affects the colon or rectum. "Claudin-2 (Cldn2) has been implicated in promoting liver metastasis in breast and colorectal cancers, while claudin-6 (Cldn6) is associated with chemotherapy resistance and poor prognosis in gastric and cervical adenocarcinomas." (PMID 40361399, 2025). "Adhesion of HT-29 colorectal cancer cells display a 2.2-fold higher ability to adhere to primary Claudin-2-expressing hepatocytes when compared to Claudin-2-deficient hepatocytes." (PMID 34079064, 2021). "Collectively, these results demonstrate that CLDN2 is upregulated in human colorectal cancers and associates with poor overall survival, suggesting its oncogenic role in colorectal cancer progression." (PMID 34965023, 2021). "We now demonstrate that Claudin-2 is functionally required for colorectal cancer liver metastasis and that Claudin-2 expression in primary colorectal cancers is associated with poor overall and liver metastasis-free survival." (PMID 34079064, 2021). "We have examined the role of Claudin-2, and other claudin family members, as potential prognostic biomarkers of the desmoplastic and replacement histopathological growth pattern associated with colorectal cancer liver metastases." (PMID 34079064, 2021). "IBD elevates the risk for developing colorectal cancer and augmented claudin-2 expression could contribute to this." (PMID 31726679, 2019). "Interestingly, claudin-2 was also detected in human colorectal cancer-associated fibroblasts (CAFs)." (PMID 31726679, 2019). "High expression of PROM1, LEMD1, CLDN2, PIGR and LCN2 were associated with CRC cell migration, promoting colorectal cancer growth and metastasis." (PMID 36816926, 2023). "In IBD and colorectal cancer, the expression levels of occludin and ZO-1 are reduced, but the expression level of claudin-2 is increased." (PMID 35865942, 2022). "Many claudins are dysregulated in a range of cancers, as in the case of the CLDN1 and CLDN2 genes, which are overexpressed in colorectal cancer." (PMID 35281827, 2022). "This study sheds light on the first mechanistic insight into CLDN2‐regulated NDRG1 expression in colorectal cancer." (PMID 34965023, 2021). "Consistently, the promoting role of CLDN2 in colorectal cancer migration/invasion was verified by wound‐healing assay with HT29 and Caco2 cells." (PMID 34965023, 2021). "To extend these observations, we assessed the ability of Claudin-2 to promote colorectal cancer liver metastases." (PMID 34079064, 2021). "Claudin-2 enhances breast cancer metastasis to the liver and increases the tumorigenicity of colorectal cancer cells." (PMID 34079064, 2021). "Taken together, our results demonstrate that colorectal cancer cells expressing Claudin-2 interact with resident hepatocytes through the formation of trans-homotypic Claudin-2/Claudin-2 interactions." (PMID 34079064, 2021). "Western blot indicated that a majority of colorectal cancer cell lines (4/8) positively expressed CLDN2 protein." (PMID 34965023, 2021). "We next assessed if the ability of colorectal cancer cells to adhere to hepatocytes was mediated through a trans-homotypic interaction between Claudin-2 molecules expressed in both cell types, as previously demonstrated for breast cancer cells." (PMID 34079064, 2021). "Claudin-2 promotes anchorage-independent growth of colorectal cancer cells and augments their survival within the blood circulation and during early seeding events by conferring anoikis resistance." (PMID 34079064, 2021). "The result that NDRG1 inhibits colorectal cancer cell proliferation and migration/invasion, partially provides evidence to support the involvement of NDRG1 in CLDN2‐mediated colorectal cancer progression." (PMID 34965023, 2021). "Taken together, the results provide the insight that CLDN2 promotes colorectal cancer progression in vitro and in vivo." (PMID 34965023, 2021).
colorectal cancer (continued). "Our study provides evidence illustrating that CLDN2 promotes colorectal cancer progression by suppressing NDRG1 expression via stabilising CLDN2/ZO1/ZONAB complex." (PMID 34965023, 2021). "Subsequent analysis of CLDN2 mRNA levels in the publicly available colorectal datasets indicated a significantly elevated expression of CLDN2 in colorectal cancers." (PMID 34965023, 2021). "To extend these analyses, we also assessed Claudin-2 expression in 22 primary colorectal cancer primary tumors and their matched liver metastases." (PMID 34079064, 2021). "Claudin-2 expression is also upregulated in the colorectal cancer while its expression in RCC is sharply inhibited." (PMID 33622361, 2021). "In contrast, overexpression of CLDN2 in colorectal cancer cells (HCT116CLND2‐GFP) revealed downregulation of E‐cadherin and upregulation of Collagen I, Fibronectin and Vimentin." (PMID 34965023, 2021). "Claudin-2 promotes protumorigenic phenotypes, including increasing anchorage-independent growth of colorectal cancer cells." (PMID 34079064, 2021). "Together, these data suggest that Claudin-2 is a critical mediator promoting colorectal cancer liver metastasis." (PMID 34079064, 2021). "As these cells are held responsible for cancer recurrence following curative resection, claudin-2 has been proposed as a novel therapeutic target in colorectal cancer." (PMID 32630408, 2020). "The bulk of existing studies on claudin-2 in the gastrointestinal tract concerns colorectal cancer, where it is upregulated in response to IL-4 and IL-13 and involved in promoting proliferation, survival, migration, colony formation, and drug resistance." (PMID 32630408, 2020). "Cancers of the gastrointestinal tract—Claudin-2 is highly expressed in gastric and colorectal cancers and its expression level shows a good correlation with the development of these tumors." (PMID 31726679, 2019). "An increase in claudin-2 expression promoted colonocyte proliferation and anchorage-independent colony formation and stimulated tumor formation in colorectal cancer xenografts." (PMID 31726679, 2019). "These proteins interacting with claudin-2 were often over expressed or activated in colorectal cancer (A ∩ E) but only Smad4 was the proteins that interacted with claudin-7 (A ∩ E)." (PMID 28698546, 2017). "In colorectal cancer, Claudin-2 levels are elevated and its expression can be detected in pre-neoplastic conditions, such as inflammatory bowel disease that pre-dispose to colon cancer formation." (PMID 25823815, 2015). "Claudin-2 enhances breast cancer liver metastasis and promotes the development of colorectal cancers." (PMID 25823815, 2015). "A previous study has demonstrated that EGFR-dependent activation of the MEK/ERK signaling pathway stimulates Claudin-2 expression in colorectal cancer cells." (PMID 25823815, 2015). "The analysis of mRNA and protein expression using a total of 309 patient samples revealed that CLDN2 expression is significantly increased in colorectal cancer, and correlates with cancer progression and tissue invasion." (PMID 24884630, 2014). "Claudin-2 overexpression has been shown to relate to epithelial weakening in lung and colorectal cancer cells, and these events are regulated by EGF-mediated signaling pathways." (PMID 24069372, 2013). "Claudin-2 is heavily up-regulated in colorectal cancer tissue compared to normal tissue from the same individual." (PMID 21310043, 2011). "In the realm of prognosis, high CLDN2 in colorectal cancer, high CLDN6/9 in endometrial cancer, or low CLDN7 in various cancers could inform risk stratification and follow-up intensity." (PMID 40687428, 2025). "Moreover, recent work demonstrated that CLDN2 is functionally required for colorectal cancer liver metastasis: silencing CLDN2 greatly impairs the ability of CRC cells to seed and survive in the liver." (PMID 40687428, 2025).
colorectal cancer (continued). "Loss of CLDN2 promotes the dissociation of the CLDN2/ZO1/ZONAB complex, which then induces ZONAB translocation to the nucleus and enrichment at the NDRG1 promotor to activate its transcription, thereby preventing the growth and spread of colorectal cancer." (PMID 36620607, 2022). "To further determine whether CLDN2 modulates the protein expression of NDRG1 in colorectal cancer cells, we performed immunoprecipitation assay in HCT116 cells." (PMID 34965023, 2021). "To uncover the underlying molecular mechanism of how CLDN2 facilitate colorectal cancer progression, we performed RNA sequencing (RNA‐seq) on CRISPR‐mediated CLDN2 knockout cells (HT29sgCLDN2 and HT29V2) and CLDN2‐expressing cells (HCT116CLDN2‐GFP and HCT116GFP)." (PMID 34965023, 2021). "This growth promoting ability of CLDN2 in colorectal cancer was further confirmed by subsequent CCK8 proliferation assay, where HT29sgCLDN2 cells were less proliferative than control cells (HT29V2) and HCT116CLDN2‐GFP cells were more proliferative than control cells (HCT116GFP)." (PMID 34965023, 2021). "To gain insights into the mechanism whether CLDN2 regulated downstream EMT genes, we next analysed the expression profiles of EMT‐signature markers in colorectal cancer cells with either stable CRISPR‐mediated CLDN2 knockout or CLDN2 overexpression." (PMID 34965023, 2021). "In addition, CLDN2 level was examined in 104 cases of colorectal cancer tumours and 85 cases of cancer adjacent normal tissues." (PMID 34965023, 2021). "We provide evidence that Claudin-2 status in patient-derived extracellular vesicles may serve as a relevant prognostic biomarker to predict whether colorectal cancer patients have developed replacement type liver metastases." (PMID 34079064, 2021). "Claudin-2 promotes anchorage-independent growth of colorectal cancer cells in soft agar." (PMID 30692208, 2019). "Furthermore, Claudin-2 expression increases the tumorigenicity of colorectal cancer cells by enabling anchorage-independent growth." (PMID 30692208, 2019). "Elevated claudin-2 expression has been reported in colorectal cancer (CRC)." (PMID 29134439, 2018). "Claudin-2 expression is also upregulated in colorectal cancer (CRC) and promotes carcinogenesis." (PMID 29152115, 2017). "CLDN2 is a transmembrane protein that has been shown to result in epithelial permeability, neoplastic transformation, significant increases in cell proliferation and anchorage-independent growth when overexpressed in colorectal cancer cells." (PMID 24884630, 2014). "Recently, claudin-2 has been reported selective up-regulated in colorectal cancer and may be useful as tumor markers and targets for the treatment of colorectal cancer." (PMID 23919729, 2013). "From a clinical point of view, high CLDN2 in colorectal cancer appears to be linked to poor outcome in those receiving 5-FU treatment and CLDN1 and CLDN7 appear to form a claudin signature to predict the clinical response to chemotherapies in colorectal cancer." (PMID 38137355, 2023). "Thus, this study suggested that CLDN2 may serve as a promising target for colorectal cancer treatment." (PMID 37621953, 2023). "Thus, colorectal cancer cells may also form replacement-type liver metastases through interactions with resident hepatocytes, which rely on the formation of trans-homotypic Claudin-2–Claudin-2 interactions between these cell types." (PMID 34079064, 2021). "Thus, we assessed whether Claudin-2 could also facilitate the ability of colorectal cancer cells to adhere to primary hepatocytes." (PMID 34079064, 2021). "Another key role of claudin-2 could be its effect on colorectal cancer stem-like cells." (PMID 31726679, 2019). "In colorectal cancer (CRC), NDRG1 downregulation was found to be essential for driving Claudin-2 (CLDN2)-mediated cell proliferation and migration/invasion in vitro and in vivo." (PMID 40332138, 2025).
colorectal cancer (continued). "In colorectal cancer (CRC), CLDN1, CLDN2, CLDN4, and CLDN18 have been shown to either be upregulated or aberrantly expressed." (PMID 38540693, 2024). "Based on the currently available body of work on the protein expression of claudins in colorectal cancer, CLDN1, CLDN2, CLDN4, and CLDN18 have all been reported to be expressed in CRC." (PMID 38540693, 2024). "An upregulation of claudin-2 was also detected in cutaneous SCC, colorectal cancer, and endometrioid endometrial adenocarcinoma, and in two-thirds of examined lung adenocarcinoma samples." (PMID 36232536, 2022). "Our findings revealed that the mRNA expression levels of CLDN1, CLDN2, CLDN12, and CLDN14 were upregulated in colorectal cancer tissues relative to normal tissues in the Oncomine database, whereas CLDN3, CLDN5, CLDN7, CLDN8, CLDN11, CLDN15, and CLDN23 were downregulated, as previously reported." (PMID 35281827, 2022). "Claudin-2 has been shown to promote anchorage-independent growth of colorectal cancer cells, although the precise domains within Claudin-2 important for this function were not determined." (PMID 30692208, 2019). "Since a previous study had confirmed the interaction between CLDN2, ZO1 and ZONAB, which was involved in human lung adenocarcinoma cell proliferation, we wondered if CLDN2 indirectly modulates the expression of NDRG1 by similarly interacting with ZO1/ZONAB in colorectal cancer cells." (PMID 34965023, 2021). "Previous studies have shown that CLDN2, CLDN6 and CLDN7 are involved in patient response to chemotherapies in cancers including breast cancer and colorectal cancer, yet with no clear mechanism identified." (PMID 38137355, 2023).